CD4 (CD4 molecule)
Diseases named in the same sentence as CD4 in open-access papers (continued):
Sharing a sentence is not in itself a finding about the gene and the disease.
COVID-19 (continued). "Collectively, the results of this multidimensional analysis reveal distinct populations of activated and proliferating CD4 T cells that were enriched in COVID-19 patients." (PMID 32669297, 2020). "The data presented here suggest that neutralizing antibodies play a role in resolving acute COVID-19, but statistical associations found less of a role for antibodies than SARS-CoV-2-specific CD4+ or CD8+ T cells." (PMID 33010815, 2020). "One CyTOF-based analysis of peripheral blood samples from COVID-19 patients found that those with severe disease had a significantly decreased number of CD4+ and CD8+ T cells compared with normal controls." (PMID 32808850, 2020). "A study about immune response of COVID-19 suggested that both CD3+CD4+ lymphocytes and CD3+CD8+ lymphocytes were lower than normal levels in COVID-19 patients, even much lower in severe cases." (PMID 33256876, 2020). "We found much higher frequencies of tp NCAP reactive CD4+ T cells in post COVID-19 compared to unexposed HC, while high tp spike reactive CD4+ T cells were found in both groups." (PMID 33424856, 2020). "CD8+ and CD4+ T cells of COVID-19 patients showed high frequencies of single-positive PD1−LAG-3+ and PD1−TIM-3+ CD8+ and CD4+ T cells with a significant increase compared to healthy controls." (PMID 32983106, 2020). "In the COVID-19 X-ray (+) patients, there was a lower proportion of effector CD4+ T cells, naïve CD8+ T cells and higher central memory CD4+ cells and effector CD8+ T cells than control." (PMID 33291439, 2020). "A model based on the combination of interleukin-8 and the numbers of CD4+ T cells and NK cells showed a good performance in predicting the death of patients with COVID-19." (PMID 32661797, 2020). "Similar to these findings, autopsy of patients with COVID-19 showed that the counts of peripheral CD4 and CD8 T cells were substantially reduced, which accounts for, in part, the severe immune injury in this patient." (PMID 32746940, 2020). "The stability of CD8 and CD4 T cell activation and PB responses during COVID-19 suggests a prolonged period of peak immune responses at the time of hospitalization or perhaps a failure to appropriately down-regulate responses in some patients." (PMID 32669297, 2020). "In this study, we provide a comprehensive quantitative analysis of the time course of viral loads, neutralizing antibody and CD4 T cell responses in 29 COVID-19 patients with different disease outcomes over the whole period of hospitalization or until death." (PMID 33262993, 2020). "In patients with COVID-19, the overall percentage of T lymphocytes is generally reduced, especially CD4+ CD3+ T lymphocytes, which have an activation phenotype, a reduction much more pronounced in severely ill patients." (PMID 33193331, 2020). "We found most unexposed and post COVID-19 HC to have SARS-CoV-2 reactive CD4+ and CD8+ T cells in similar frequencies." (PMID 33424856, 2020). "To further characterize the expression pattern of LAG-3 and TIM-3 we examined the co-expression of PD1/LAG-3 and PD1/TIM-3 on CD8+ and CD4+ T cells of COVID-19 and malaria patients compared to healthy controls." (PMID 32983106, 2020). "The results of flow cytometry showed that the lower lymphocyte count in COVID-19 was largely attributed to the decrease in number of T lymphocytes including CD4+ T cells and CD8+ T cells." (PMID 32727465, 2020). "Here we show that COVID-19 patients have reduction in absolute numbers of CD4+ and CD8+ T lymphocytes, which display markers related to activation or exhaustion/senescence, along with altered expression of master regulators and of several chemokine receptors." (PMID 32632085, 2020). "COVID-19 T cell responses showed notably higher frequency of S-specific CD4+ T cell responses, whilst the majority of CD8+ responses were to M, N and ORF proteins." (PMID 33362759, 2020).
COVID-19 (continued). "In analogy to patients infected with SARS-CoV or MERS-CoV, CD4 Th1-cells expressing GM-CSF, and IL-6 were isolated from patients with COVID-19 CRS." (PMID 33154972, 2020). "We observed higher median proportion of central memory CD4+ T cells in COVID-19 X-ray (+) patients than in CD4+ T cells in COVID-19 X-ray (−) and significantly the lowest in healthy control (respectively, 39.5% vs. 32.2% vs. 1.8%, p < 0.0001)." (PMID 33291439, 2020). "Analysis of 125 hospitalized COVID-19 patients revealed that although CD4 and CD8 T cells were activated in some patients, T cell responses were limited in others." (PMID 32669297, 2020). "In the COVID-19 patients in the general, severe and critical groups, the numbers of peripheral lymphocytes and CD4+ T lymphocytes and the ratio of CD4+/CD8+ lymphocytes were significantly lower than those in the normal control group." (PMID 32976531, 2020). "Given the characteristics of our study and the data observed for CD3+CD4+ T cells at hospital admission, we decided to assess the performance of lymphocyte subsets as a predictive factor for critical COVID-19." (PMID 33182268, 2020). "A large body of evidence suggests functional exhaustion of CD8+ T and CD4+ T cells in the peripheral blood of COVID-19 patients." (PMID 33335518, 2020). "Nevertheless, the role of neutrophils and CD4+ T cells during the development of COVID-19 warrants further investigation." (PMID 32492165, 2020). "The dysregulation of the adaptive immune response in the severe patient group with COVID-19 in Wuhan (China) was probably a pronounced decrease of CD4+, CD8+, and regulatory T cells, which hastens the exceptional production of proinflammatory cytokines." (PMID 33212762, 2020). "For patients with COVID-19, CD4+ T-cell counts were found to be lower than the normal levels in 45.4% of patients, while the CD4/CD8 ratio was similar to that of healthy controls in 92.8% patients." (PMID 32627758, 2020). "A decrease of CD4+ effector cells in COVID-19 patients was also observed by other researchers, in patients with moderate and severe type of COVID-19 infection compared to healthy volunteers." (PMID 33291439, 2020). "Flow cytometric analysis of severe COVID-19 patients demonstrates a remarkable reduction of lymphocytic T Cells (CD4+ and CD8+) and natural killer (NK) cells." (PMID 32851877, 2020). "Our understanding of the role of T-cell mediated immunity (CMI) in COVID-19 is only just being teased out, but a number of studies report virus-specific CD4+ and CD8+ T cells in COVID-19 individuals, particularly CD8+ T cells." (PMID 33195319, 2020). "Although a decrease of CD4+ T cells was common in adult patients with severe and moderate COVID-19,16 this was rarely seen in pediatric patients (3 [1.9%]), and even increased in 14 moderate cases (15.9%)." (PMID 32492165, 2020). "In mild and severe COVID-19, instead, the increase of activated CD4+ T cells reflects the ongoing immune activation." (PMID 33391280, 2020). "In several studies, a decline in CD8+ was more frequently observed in COVID-19 patients than a decline in CD4+." (PMID 32695683, 2020). "Phenotypic profiling of circulating leukocytes in critical COVID-19 patients indicates high activation of S-protein specific T-cells producing inflammatory cytokines, coupled with depletion of CD4+ and CD8+ T-cells expressing the LFA-1 integrin subunit CD11a." (PMID 32848776, 2020). "Another CyTOF-based study demonstrated that COVID-19 patients with mild disease severity had increased proportions of dendritic cells, macrophages, CD4+ T cells, and TGFβ+CD28– naïve CD8+ T cells when compared with those with severe disease." (PMID 32808850, 2020). "In patients with severe COVID-19, but less so in patients with mild disease, lymphopenia is commonly observed, with drastically reduced numbers of B cells, helper (i.e. CD4+) T cells (THs), cytotoxic (i.e. CD8+) T cells (CTLs) and NK cells." (PMID 32671650, 2020).
COVID-19 (continued). "A study of 39 COVID-19 patients with pneumonia revealed that CD4+ and CD8+ T cells were low in the peripheral blood but have an increased capability to produce IL-17 in vitro compared to controls." (PMID 33042116, 2020). "Higher CD4+ T lymphocyte count was correlated with shorter time of detoxification for feces of COVID-19 patients." (PMID 33336061, 2020). "These suggest that CD4+ T-cells in severe COVID-19 patients are highly activated in the lung, recruiting macrophages, T-cells, and other immune cells." (PMID 33178221, 2020). "In COVID-19 patients, the counts and percentages of CD4+ T cells, CD8+ T cells and NKT cells were significantly decreased than healthy volunteers." (PMID 33154753, 2020). "We observed a significantly higher percentage of plasmablasts and lower CD4+ lymphocytes in COVID-19 X-ray (+) patients than in COVID-19 X-ray (−) and control." (PMID 33291439, 2020). "Stimulation of PBMC with MP_S and MP_CD4_R led to consistent activation of SARS-CoV-2-specific CD4+ T cells in PBMC obtained from COVID-19 ARDS patients." (PMID 32591408, 2020). "Although decreased blood lymphocyte count of COVID-19 patients has been widely reported, lymphocytes were shown to be activated as the increases in the expression of HLA-DR in CD4+ and CD8+ cells, the percentage of CD4+ CCR4+ CCR6+ Th17 cells." (PMID 32733921, 2020). "The CD8+ T-cell response has been shown to be critical for resolving SARS-CoV-2 infection, although virus-specific CD4+ T-cells have been detected more often than specific CD8+ T-cells in recovered COVID-19 patients." (PMID 33362759, 2020). "PLWHA has comparable COVID-19 morbidity rates as the general population, and older age, low CD4 count, long length since HIV diagnosis, and treatment-naive were potential driving forces of COVID-19 occurrence among PLWHA." (PMID 32818208, 2020). "The senescence in T cells (inverted CD4+/CD8+ T cell ratio; increased frequency and proportion of senescent T cells) increases infection susceptibility to novel pathogens, such as COVID-19." (PMID 33212762, 2020). "CD69 was more frequently expressed on CM, TM, and EMRA CD8+ and CD4+ T cells in COVID-19 and malaria patients compared to the respective subsets of T cells in healthy individuals." (PMID 32983106, 2020). "As a result, we found that the signaling pathways of “cytokine production” and “leukocyte cell-cell adhesion” are the most commonly upregulated in either the CD4+ or the CD8+ T cell sets of the COVID-19 patients." (PMID 32796814, 2020). "Taken together, despite strong lymphopenia affecting both CD4+ and CD8+ T cells, and lower levels of polyclonal SEB-reactive CD4+ T cells, patients with severe COVID-19 were capable of mounting high levels of SARS-CoV-2–specific T cells." (PMID 32937615, 2020). "A decrease in Tc cells appeared to be more dominant; thus, the Th/Tc (CD4+/CD8+) ratio was often increased in COVID-19 patients." (PMID 33061829, 2020). "COVID-19 patients show a substantial reduction in the numbers of peripheral CD4 and CD8 T cells, with the remaining cells exhibiting a hyperactivated status (CD38+ HLA-DR+) and are enriched for pro-inflammatory C-C chemokine receptor 6 (CCR6+) Th17 T cells." (PMID 33302366, 2020). "Using a large pool of peptides representing predicted T‐cell epitopes, SARS-CoV-2-specific CD8+ and CD4+ T lymphocytes were identified in ~70 and 100% of COVID-19 convalescent patients, respectively." (PMID 32671650, 2020). "In COVID-19, a sustained decrease in CD4+ and CD8+ T cells, especially CD8+ T cells, is observed, despite an increase in IL-6, IL-10, IL-2, IFN-γ levels, and neutrophil counts." (PMID 33335532, 2020). "In COVID-19 patients, the numbers of CD4+ and CD8+ T cells decreased, while the levels of IL-6 and IL-10 increased in severe cases." (PMID 33028689, 2020). "During the memory phase, it was shown that all convalescent COVID-19 patients have antigen-specific CD4 T cells, and about 70 % of the patients have antigen-specific CD8 T cells." (PMID 33262067, 2020).
COVID-19 (continued). "Severe COVID-19+ individuals had significantly lower proportions of T cells (p<0.0001), as well as total CD4+ and CD8+ T cells." (PMID 32669287, 2020). "The previously reported modifications in severe forms of COVID-19 showed increased levels of C-reactive Protein [CRP], ferritin, lactate dehydrogenase [LDH]), associated with a marked lymphopenia of CD4 and CD8 T-cell subsets." (PMID 33178207, 2020). "Despite the lymphopenia, expanded virus-specific CD8+ and CD4+ T cells can be detected in COVID-19 patients." (PMID 32948688, 2020). "Another study reported that decreased CD4+ T cells were more evident in the peripheral blood of patients with severe COVID-19." (PMID 33317643, 2020). "Lymphopenia is one of the most salient markers of COVID-19 and it seems to arise as the result of the reduction of all lymphocyte populations, including CD4+ and CD8+ T cells, B cells, and NK cells." (PMID 33382687, 2020). "CD4:CD8 ratios were increased in COVID-19 patients when compared to HC (5.5 ± 3.0 in COVID-19 vs 2.3 ± 0.9 in HC, p=0.0115)." (PMID 32591408, 2020). "In general population, COVID-19 asymptomatic patients seem to have less decrease in CD4+ lymphocyte counts and a shorter duration of viral shedding, but this has not yet been reported in cancer patients." (PMID 33082850, 2020). "The same statistical trend toward higher CD69 frequencies was evident in the EM subset of CD8+ and CD4+ T cells in COVID-19 and malaria patients compared to healthy controls." (PMID 32983106, 2020). "Interestingly, we found that COVID-19 patients with neutrophilia, lymphopenia and a more pronounced alteration in the biochemical parameters associated to inflammation had a higher percentage of CD4+ T cells with expression of activation markers HLA-DR and CD38." (PMID 33324414, 2020). "As CD4+ T cells play a critical role in orchestrating responses against viral infections, important lessons can be drawn by comparing T cell response in COVID-19 and in HIV infection and by studying HIV-infected patients who became infected by SARS-CoV-2." (PMID 33384690, 2020). "Nevertheless, the frequency of the KI67+ or CD38+HLA-DR+ CD8 and CD4 T cell responses in COVID-19 patients was similar in magnitude to those of other acute viral infections or live attenuated vaccines in humans." (PMID 32669297, 2020). "Preliminary data from China indicate that patients with moderate or severe COVID-19 have reduced or very reduced (<200/μL) numbers of CD4 cells." (PMID 32574323, 2020). "CD4+ T cells and monocytes are considered as the primary sources of high IL-6 levels in COVID-19, which in turn correlate with decreased monocytic HLA-DR expression, one of the hallmarks of the disease." (PMID 33239683, 2020). "Restricted functionality of SARS-CoV-2–specific CD4+ T cells in patients with a severe course of COVID-19." (PMID 32937615, 2020). "We analyzed viral loads, virus-specific antibody, and CD4 T cell responses in 29 COVID-19 patients over the entire period of their hospitalization." (PMID 33262993, 2020). "Even though the total CD4+ T cell count is also reduced in COVID-19 patients, the proportion of CD4+ T cells (amongst lymphocytes) appears to remain constant, with numbers of central memory CD4+ T-cells found to be markedly increased in severe disease." (PMID 33362759, 2020). "How to effectively increase the number of CD4+ T lymphocytes in the peripheral blood of patients with COVID-19 still requires further study." (PMID 32976531, 2020). "The analysis of lymphocyte subsets in the clinical charts showed a significant generalized decrease of the T lymphocyte count affecting both CD8+ and CD4+ T cells with a resulting normal CD4/CD8 ratio in COVID-19 patients." (PMID 32983106, 2020). "Lymphopenia (in CD4+ and CD8+ T cells) and decreased IFN-γ expression in CD4+ T cells are also associated with severe COVID-19." (PMID 32952832, 2020).
COVID-19 (continued). "The correlation coefficient of the number of peripheral blood CD4+ T lymphocytes and the number of total lymphocytes in the 35 COVID-19 patients was 0.9051 (p = 0.000002, <0.01)." (PMID 32976531, 2020). "It has been reported that parsimonious models, which contain five features (age, lactate dehydrogenase, C-reactive protein, CD4+ T-cell counts, and mass of infection), are an ideal measure for predicting COVID-19 severity." (PMID 32584780, 2020). "Another important study corroborated these findings and demonstrated presence of SARS-CoV2 S protein reactive CD4+ T cells in 83% COVID-19 patients and in upto 34% seronegative healthy controls." (PMID 33133083, 2020). "Our study has shown that CD4+ T-cells in severe COVID-19 patients have dysregulated activation and differentiation mechanisms." (PMID 33178221, 2020). "Coordinated SARS-CoV-2-specific adaptive immune responses were associated with milder disease, suggesting roles for both CD4+ and CD8+ T cells in protective immunity in COVID-19." (PMID 33010815, 2020). "Overall, the CD4+ T cell response in acute COVID-19 cases largely consisted of TFH cells and IFNγ-producing cells, consistent with proper antiviral polarization." (PMID 33010815, 2020). "In agreement with published observations, COVID-19 patients displayed low or reduced numbers of lymphocytes, including both CD4+ and CD8+ T cells and B cells." (PMID 32707842, 2020). "Analysis of SARS-CoV-2-specific adaptive immune responses during acute COVID-19 identifies coordination between SARS-CoV-2-specific CD4 T cells and CD8 T cells to limit disease severity." (PMID 33010815, 2020). "Projecting the global CD4 T cell differentiation patterns into the high-dimensional tSNE space again identified major alterations in the CD4 T cell response in COVID-19 patients compared with HDs and RDs." (PMID 32669297, 2020). "Coordinated SARS-CoV-2-specific adaptive immune responses are associated with milder disease, suggesting roles for both CD4+ and CD8+ T-cells in protective immunity in COVID-19, and are disrupted in older adults." (PMID 33362793, 2020). "In one clinical case of mild COVID-19, antibody producing cells and T cell immune responses (CD4 + and CD8 + T cells) reached peak levels prior to resolution of symptoms and were concurrently maintained at a steady level during the convalescence phase." (PMID 32922406, 2020). "CD4+ T cell count for COVID-19 patients in the glucocorticoids group was lower than that in the healthy control group during hospitalization, with the lowest at 7-9 days and a peak at 10-12 days, with statistically significant differences (P < 0.05)." (PMID 33015160, 2020). "This study, which included patients at time of admission, showed a significantly decrease in the total CD3+CD4+ T cells count, in the CD4+/CD8+ ratio, and in the CD4+MFI, which were linked to a critical evolution of COVID-19 patients with bilateral pneumonia." (PMID 33182268, 2020). "In our study we observed significantly lower median proportion of CD4+ cells and higher median proportion of neutrophils in COVID-19 X-ray (+) than in COVID-19 X-ray (−)." (PMID 33291439, 2020). "Due to lack of sufficient information about the expression levels of Tregs and its role in regulation of IL-6 cascade in COVID-19 patients, this study aimed to evaluate the expression level of IL-6 and CD4+ Foxp3+ CD25+T cells in COVID-19 patients." (PMID 33244382, 2020). "Overall, experience in HIV clinical management and past clinical trials represent a special use case for innovative studies aiming at increasing CD4+ T cell function and reducing COVID-19 morbidity." (PMID 33384690, 2020). "Lower frequencies of IFNγ producing CD4+ T cells in severe COVID-19 were confirmed in another study." (PMID 33133083, 2020).